OR2V2 (olfactory receptor family 2 subfamily V member 2)
Description:
Odorant receptor.
Synonyms: OR2V3; OST713
Tractability: Small molecule: it belongs to a druggable protein family. Antibody: UniProt places it where antibodies can reach, with medium confidence; UniProt predicts a signal peptide or a membrane-spanning region; its Gene Ontology location is reachable by antibodies, with medium confidence.
Gene: Protein-coding gene on chromosome 5 (181,147,586 to 181,159,285, forward strand). Ensembl gene ENSG00000182613.
Subcellular location: Cell membrane
Pathways (Reactome):
Sensory Perception: Expression and translocation of olfactory receptors
Gene Ontology:
Molecular function: olfactory receptor activity; G protein-coupled receptor activity
Biological process: detection of chemical stimulus involved in sensory perception of smell; G protein-coupled receptor signaling pathway
Cellular component: plasma membrane; membrane
Genetic constraint (gnomAD): Loss-of-function variants: 0 observed, 0.62 expected, observed/expected ratio (o/e) 0, 90% interval 0 to 1.81. That is too few expected variants to judge how well the gene tolerates losing a copy. Missense variants: 392 observed, 405.58 expected, observed/expected ratio (o/e) 0.97, 90% interval 0.89 to 1.05. Synonymous variants: 161 observed, 157.66 expected, observed/expected ratio (o/e) 1.02, 90% interval 0.9 to 1.16.
Homologues: Orthologues: chimpanzee OR2V2 (99% identical), guinea pig OR2V2 (86% identical), rat Or2v2b (85% identical), rat Or2v2 (84% identical), rat Or2v2c (84% identical), mouse Or2v2 (83% identical). Paralogues in human: OR2V1 (87% identical), OR2T33 (55% identical), OR2M2 (54% identical), OR2T12 (54% identical), OR2T8 (54% identical), OR2M5 (53% identical), OR2T1 (53% identical), OR2T2 (53% identical), OR2T35 (53% identical), OR2M4 (53% identical), OR2M3 (53% identical), OR2M7 (52% identical), and 80 more.